CST3 (cystatin C)
Diseases named in the same sentence as CST3 in open-access papers (continued):
Sharing a sentence is not in itself a finding about the gene and the disease.
COVID-19 (continued). "Admission levels of ln-transformed cystatin C were also positively associated with the mortality among COVID-19 patients, which indicated that higher ln-transformed cystatin C levels might imply higher death rates during hospitalization of patients with COVID-19." (PMID 33061826, 2020). "The current data indicate that cystatin C levels are significantly higher in patients with critical illness compared to those with severe COVID-19, suggesting its role in predicting adverse outcomes." (PMID 40861638, 2025). "Paradoxically, many studies on COVID-19 have reported a positive correlation between elevated serum and urine CST3 levels and mortality." (PMID 39062796, 2024). "Our MR analysis demonstrated that kidney function plays a stronger role in COVID-19 than the serum levels of cystatin C or creatinine." (PMID 38225574, 2024). "On the other hand, in the saliva of patients with moderate or severe COVID-19, CST3 levels have been observed to be decrease with respect to healthy individuals." (PMID 39062796, 2024). "The area under the ROC curve for serum cystatin C for predicting COVID-19 severity and mortality for 0.904 and 0.768, respectively (p<0.001)." (PMID 37593314, 2023). "The study demonstrated that patients with severe COVID-19 illness had elevated levels of serum Cystatin C." (PMID 37593314, 2023). "When designing the chip we included Cystatin C for its potential as being predicative of renal injury and due to its observed elevated levels in COVID-19 patients." (PMID 37064248, 2023). "Serum Cystatin C level of more than 1.28mg/dL predicted COVID-19 severity with a sensitivity of 95.12% and specificity of 100%." (PMID 37593314, 2023). "This study aims to investigate the relationship between Cystatin C and other inflammatory factors with the consequences of COVID-19." (PMID 37217858, 2023). "As per the current study, the area under the ROC curve for serum cystatin C for predicting COVID-19 severity and mortality for 0.904 and 0.768, respectively (p<0.001)." (PMID 37593314, 2023). "Similar studies have shown cystatin C increase in severely ill patients and that it can be used as a predictive marker for mortality in COVID-19 patients." (PMID 37704948, 2023). "The area under receiver operating characteristic curves (ROC) for serum cystatin C for predicting COVID-19 severity and mortality was 0.904 and 0.768, respectively (p<0.001)." (PMID 37593314, 2023). "The AUC value of serum Cystatin C to predict COVID-19-related AKI was 0.96 (0.90 to 1.0), with the best cutoff value of 1.00 mg/L." (PMID 36974657, 2023). "The current study demonstrated that serum levels of cystatin C done at the time of admission were statistically elevated among patients with severe COVID-19 illness compared to patients with mild COVID-19 illness." (PMID 37593314, 2023). "In our study, 34% of patients with COVID-19 expired in the hospital, and the baseline cystatin C level of these patients was significantly higher than alive patients." (PMID 37217858, 2023). "Deterioration in kidney function is another emerging health problem in COVID-19 patients, and the predictive value of serum cystatin C in the prognosis of these patients is rarely reported." (PMID 35054276, 2022). "This meta-analysis also shows the potential use of Cystatin C as a prognostic marker of patients with COVID-19 and the early diagnosis of AKI and other subsequent renal disorders." (PMID 36361485, 2022). "In our study, in the IG(−) group and in the C1 and C14 time-points in the COVID-19 group, a positive correlation between cystatin C and NGAL was observed." (PMID 35054276, 2022). "The results of our meta-analysis show the potential clinical role of Cystatin C in predicting severe COVID-19 in patients." (PMID 36361485, 2022).
COVID-19 (continued). "These function in inflammation (e.g. C-reactive protein), coagulation and vascular dysfunction (e.g. von Willebrand factor), complement cascade (e.g. Complement C1q subcomponent subunit C), and other biological processes altered by COVID-19 (e.g. Cystatin C)." (PMID 35702332, 2022). "Abnormalities in cystatin C levels occur earlier than with creatinine, and elevated cystatin C levels on admission have a better predictive value for COVID-19 severity." (PMID 33828483, 2021). "Several enzymes with antimicrobial activity are increased in COVID-19 patients’ sera, including CST3, DEFA1, and LYZC, indicating a possible secondary bacterial infection [TE97]." (PMID 34876157, 2021). "For markers associated with kidney injury, the levels of creatinine (Cr), blood urea nitrogen, and cystatin C were abnormally high in severe/critical COVID-19 as early as 1–2 dpi, followed by a rapid decrease before becoming plateaued after 10 dpi." (PMID 34103487, 2021). "Our results indicated that creatinine and cystatin C were increased, eGFR was decreased in severe COVID-19 patients." (PMID 33557785, 2021). "We also performed a ROC curve analysis to determine the predictive value of cystatin C and creatinine for disease severity in COVID-19 patients." (PMID 33828483, 2021). "This is the first study to evaluate renal dysfunction following COVID-19 using cystatin C as an indicator." (PMID 33828483, 2021). "Subsequent analysis via the Kaplan-Meier methods revealed that overall COVID-19 patients with a baseline cystatin C level ≥ 1.36 mg/L had significantly worse outcomes, compared to those with cystatin C levels < 1.36 mg/L (P value < 0.0001)." (PMID 33061826, 2020). "Firstly, clinical features of COVID-19 patients were compared under the quartile classification of baseline cystatin C levels (less than 0.90, 0.90 to 1.08, 1.08 to 1.36, and more than 1.36 mg/L, respectively)." (PMID 33061826, 2020). "The occurrence of critically ill COVID-19 was more prevalent in the highest cystatin C group, with APACHE II and SOFA scores ascending (all P values for trend < 0.05)." (PMID 33061826, 2020). "The prevalence of critically ill COVID-19 ascended with increasing ln-transformed cystatin C levels, and a gradual tendency of the gentle curve was observed around ln-transformed cystatin C levels of more than 1.50 mg/L." (PMID 33061826, 2020). "First, the incidence rates of ARDS and critically ill COVID-19 were obviously higher among patients with the highest cystatin C level, who were also accompanied by elevated lactate levels, but a reduced PaO2:FiO2 ratio." (PMID 33061826, 2020). "In this study, a myocardial injury prediction model for COVID-19 patients based on clinical parameters was successfully constructed used age, history of alcohol consumption, diastolic blood pressure, heart rate, body mass index, and cystatin C." (PMID 40587665, 2025). "Further supporting the similarity between bacterial sepsis and COVID-19-induced viral sepsis, we observed an elevation of factors associated with oxidative stress (e.g., MPO) and factors released from damaged (organ) tissue (NGAL, Cystatin C, myoglobin)." (PMID 36851312, 2023). "This meta-analysis evaluated the serum Cystatin C levels of patients with COVID-19." (PMID 36361485, 2022). "It is necessary to consider whether the relatively low concentration of cystatin C and high cholesterol in COVID-19 are part of the pathogenesis or a result of the disease." (PMID 35054276, 2022). "Interestingly, cystatin C values in healthy adults range from 0.6 to 1.0 mg/L, while COVID-19 patients with cystatin C levels of 0.80 mg/L or greater were shown to be at a high risk of death." (PMID 35054276, 2022). "In addition, the levels of WBC, NE, LYM, ALP, phosporous, urea nitrogen, cystatin C and CK-MB were also related to severe COVID-19." (PMID 34397917, 2021).
COVID-19 (continued). "The other independent risk factors for COVID-19 infection included older age, male sex, black ethnicity, socioeconomic deprivation, longstanding illness and reduced renal function as measured by cystatin C, the latter also notable given renal complication in severe COVID-19." (PMID 33444201, 2020). "In other words, higher cystatin C levels on admission might predict significantly worse outcomes for adult patients with COVID-19." (PMID 33061826, 2020). "In this hospital-based study of 481 adult patients confirmed as COVID-19, we revealed that baseline serum cystatin C might serve as a potential inflammatory biomarker, independently predicting poor outcomes for SARS-CoV-2 infection." (PMID 33061826, 2020). "The highest cystatin C level (≥1.31 mg/L) was an independent risk factor for critically ill COVID-19 and all-cause death in patients without CKD, after adjustment for the underlying confounders (all P values < 0.05)." (PMID 33061826, 2020). "i.e., investigate the outcome of COVID-19 in patients with high levels of cystatin C." (PMID 32429099, 2020). "Monitoring cystatin C during in-hospital stays may thus be of clinical importance in the prognosis for adult patients with COVID-19." (PMID 33061826, 2020). "ln-transformed cystatin C levels were also independently associated with the risks for critical illness and mortality among COVID-19 patients without CKD (all P values < 0.05)." (PMID 33061826, 2020). "As a potential inflammatory marker, increasing baseline levels of serum cystatin C might independently predict adverse outcomes for COVID-19 patients." (PMID 33061826, 2020). "Serum cystatin C could be routinely monitored during hospitalization, which showed clinical importance in prognosticating for adult patients with COVID-19." (PMID 33061826, 2020). "In addition, Cystatin C could be used as a marker of renal complications in COVID-19 other than AKI, due to the need to monitor patients even longer after leaving the hospital." (PMID 36361485, 2022). "According to our research, severe SARS-CoV-2 infection may cause kidney injury since Cystatin C levels were considerably higher in patients with severe COVID-19 illness than in patients with non-severe COVID-19." (PMID 36361485, 2022). "The high ranking of cystatin C also indicates that this measure may better reflect renal function than urea or creatinine (which were also included in our analysis), and may serve as a superior predictor for COVID-19 severity." (PMID 34591027, 2021). "Firstly, the causal relationship between serum cystatin C and COVID-19 outcomes could not be concluded, due to the nature of an observational research." (PMID 33061826, 2020). "Therefore, circulating cystatin C could serve as a potential inflammatory target for preventing COVID-19 from the likely progression of critical illness and in-hospital death, not just representing kidney function." (PMID 33061826, 2020). "However, much is still unknown because of the limited number of associated single nucleotide polymorphisms (SNPs) of COVID-19 and the lack of cystatin C testing." (PMID 38225574, 2024). "In conclusion, cystatin C and other inflammatory factors such as ferritin, LDH and CRP can help the physician predict the consequences of COVID-19." (PMID 37217858, 2023). "cystatin C and other inflammatory factors such as ferritin, LDH and CRP can help the physician predict the consequences of COVID-19." (PMID 37217858, 2023). "For these reasons, we decided to conduct a review and meta-analysis on the prognostic role of Cystatin C and its predictive role regarding the occurrence of AKI in patients with COVID-19." (PMID 36361485, 2022). "Further analysis indicated that cystatin C was negatively correlated with IL-6 (r=− 0.472, P=0.001) and eGFR was inversely correlated with CRP (r=− 0.210, P=0.012) among COVID-19 patients." (PMID 33557785, 2021).
COVID-19 (continued). "Cystatin C also influences the release of key inflammatory mediators such as TNF-α, IL-12, IL-10, and nitric oxide, contributing to inflammation and potential multi-organ failure in severe COVID-19 cases." (PMID 40649865, 2025). "Kidney function assessed using creatinine and cystatin C levels over time is not affected by ongoing COVID-19 with mild to moderate severity." (PMID 35054276, 2022). "Cystatin C levels in COVID-19 severe vs. non-severe groups varied and amounted to 1.485 ± 1.191 vs. 1.014 ± 0.601 mg/dL, respectively (SMD = 1.81; 95%CI: 1.29 to 2.32; p < 0.001)." (PMID 36361485, 2022). "Finally, using a Bayesian Network model, we identified FOS, CXCL8, IL1β, CST3, PSAP, CD45 and CD74 as predictors of the COVID-19 disease." (PMID 36532041, 2022). "Pooled analysis of Cystatin C levels in COVID-19 severe vs. non-severe groups varied and amounted to 1.485 ± 1.191 vs. 1.014 ± 0.601 mg/dL, respectively (SMD = 1.81; 95%CI: 1.29 to 2.32; p < 0.001)." (PMID 36361485, 2022). "Importantly, above immune findings were used for a Bayesian network model, which significantly revealed FOS, CXCL8, IL1β, CST3, PSAP, CD45 and CD74 as COVID-19 severity predictors." (PMID 36532041, 2022). "In addition, increased baseline levels of serum cystatin C were significantly related to higher levels of blood creatinine, higher APACHE II scores, and critical illness in COVID-19 (all P values < 0.05)." (PMID 33061826, 2020). "Notably, some proteins, such as C3 or CST3 are increasing in the presented cohort but not across all COVID-19 studies." (PMID 41430040, 2025). "However, genetically instrumented COVID-19, regardless of phenotype, was not related to log-eGFR, as calculated by either the serum levels of creatinine or cystatin C." (PMID 38225574, 2024). "Moreover, elevated plasma suPAR and cystatin C levels serve as valuable prognostic markers, offering insights into the short-term morbidity and mortality risks among COVID-19 patients, regardless of AKI occurrence." (PMID 38003685, 2023). "Cystatin C also may be employed as a trustworthy biological marker to predict AKI, particularly in assisting with early clinical identification of AKI, and AKI in hospitalized patients with COVID-19 is as high as 43%." (PMID 36361485, 2022). "An interesting observation was a significant, moderate negative correlation between cystatin C and total cholesterol in each of the time-points in the COVID-19 group (C1: Rs = −0.51, p < 0.01; C7: Rs = −0.52, p < 0.01; C14: Rs = −0.65, p < 0.01; C28: Rs = −0.66, p < 0.01)." (PMID 35054276, 2022). "Additionally, three studies reported Cystatin C levels among patients with COVID-19 with and without AKI." (PMID 36361485, 2022). "Moreover, none of the participants, including COVID-19 patients, had significantly elevated cystatin C levels above normal values (>1.1 mg/L)." (PMID 35054276, 2022). "However, the clinical significance of dynamic changes in renal function indicators has not been studied, and no studies have evaluated the renal function in COVID-19 patients by cystatin C." (PMID 33828483, 2021). "Notably, in severe/critical COVID-19 patients in the recovery stage, the proportion of CD14 monocytes (based on the expression of the marker genes CST3, LYZ, CD14) in PBMCs were elevated, but CD4 T cells (IL7R, LTB) were decreased, consistent with a previous report." (PMID 35046942, 2021). "We thus reckon that circulating cystatin C may function as a potential biomarker of systemic inflammation during the exacerbation of COVID-19, rather than only reflecting renal function in patients infected by SARS-CoV-2." (PMID 33061826, 2020). "Moreover, increasing baseline levels of cystatin C were independently related to the risks of occurring critical illness and in-hospital death either in overall COVID-19 patients or in COVID-19 patients without CKD." (PMID 33061826, 2020). "However, no studies have evaluated the renal function of COVID-19 patients by cystatin C." (PMID 33828483, 2021).
breast cancer (35 papers, 2009 to 2026). A primary or metastatic malignant neoplasm involving the breast. "The serum creatinine-cystatin C ratio is an independent predictor of 1-year mortality risk in advanced breast cancer, with higher levels associated with significantly reduced mortality." (PMID 41383336, 2025). "A large-scale retrospective clinical study involving 3,060 patients with various malignancies (including breast cancer) demonstrated a significant association between serum creatinine to cystatin C ratio and survival outcomes in cancer patients." (PMID 41383336, 2025). "For cystatin-C our data suggest a possible inverse association with breast cancer risk, although this association was statistically significant only in multi-variate adjusted risk models or when cases diagnosed within the first 2 years were excluded." (PMID 34935094, 2022). "To test the potential of CIRBP-mediated regulation of these targets in breast cancer development, we focused on Cystatin C (CST3), one of the most highly interconnected genes, encoding a protein that displays tumor suppressive capacities." (PMID 33172965, 2021). "After adjustment for breast cancer risk factors, associations remained for the DNAm-predictors of cystatin C (HR: 1.37 95% CI: 1.16, 1.62, P<0.001) and leptin (HR: 1.12 95% CI: 1.03, 1.21, P=0.01)." (PMID 31848323, 2019). "CysC is a member of the CysC superfamily that is encoded by the housekeeping gene CST3 and is associated with numerous immunological processes, which results in inflammatory autoimmune diseases and tumor development (multiple myeloma and breast cancer)." (PMID 37853350, 2023). "PGS for serum cystatin C levels (T3) was associated with longer disease-free survival (HR = 0.82, 95% CI = 0.71–0.95), breast event-free survival (HR = 0.74, 95% CI = 0.61–0.91), and breast cancer–specific survival (HR = 0.72, 95% CI = 0.54–0.95)." (PMID 37377609, 2023). "Our findings support this hypothesis given that PGS for elevated cystatin C levels were associated with better breast cancer survival outcomes." (PMID 37377609, 2023). "The PGS for serum cystatin C levels was associated with longer disease-free survival (T3: HR = 0.82, 95% CI = 0.71–0.95), breast event-free survival (T3: HR = 0.74, 95% CI = 0.61–0.91), and breast cancer–specific survival (T3: HR = 0.72, 95% CI = 0.54–0.95)." (PMID 37377609, 2023). "Finally, we observed increased genetically predicted cystatin C levels to be associated with better disease-free, breast event-free, and breast cancer–specific survival." (PMID 37377609, 2023). "Cystatin-C was inversely associated with breast cancer risk and directly associated with CVD risk." (PMID 34935094, 2022). "Interestingly, the DNAm-predictors of leptin and cystatin C that are components of DNAm GrimAge were strongly associated with breast cancer incidence, even after adjustment for breast cancer risk factors." (PMID 31848323, 2019). "Conversely, associations for the DNAm-predictors of cystatin C and leptin were robust to adjustment and may be useful DNAm-based markers for predicting breast cancer." (PMID 31848323, 2019). "Therefore, to reveal the function of cystatin C at different stages of tumor progression and metastasis in vivo, we employed a mammary tumor virus (MMTV) Polyoma Middle T (PyMT) transgenic mouse model of mammary cancer and crossed it with cystatin C-deficient mice." (PMID 29088746, 2017). "This study represents the first investigation into the association between the creatinine/cystatin C ratio (CCR) and 1-year all-cause mortality among breast cancer patients in the Zhanjiang population of China." (PMID 41383336, 2025).